ERBB2 (erb-b2 receptor tyrosine kinase 2)
Diseases named in the same sentence as ERBB2 in open-access papers (continued):
Sharing a sentence is not in itself a finding about the gene and the disease.
gastric cancer (continued). "In the Lapatinib (Tykerb) with Paclitaxel (Taxol) in Asian ErbB2+ (HER2+) Gastric Cancer Study (TYTAN), for example, patients across five Asian countries are to be randomly assigned to lapatinib (1,500 mg daily) plus paclitaxel (80 mg/m2 weekly) or paclitaxel alone." (PMID 23563986, 2014). "In addition, miR-375 expression levels were markedly reduced in ERBB2-positive gastric cancer tissues." (PMID 24926380, 2014). "Correlation of Flotillin2 and erbB2 expression with clinicopathologic parameters in gastric cancer." (PMID 23658725, 2013). "Gastric cancer patients with 17q12–q21 amplification may benefit from treatment with Herceptin, a humanized antibody, designed to target and block the function of ERBB2." (PMID 22539939, 2012). "Nevertheless, the result clearly suggests that amplification of 17q12–q21 may represent a key mechanism for high levels of ERBB2 expression in a subset of human gastric cancer samples." (PMID 22539939, 2012). "A genome-wide single nucleotide polymorphism microarray analysis was performed using three cell lines of differentiated gastric cancers, and 22 genes (including ERBB2) in five highly amplified chromosome regions (with a copy number of more than 6) were identified." (PMID 22591714, 2012). "However, only has trastuzumab, which is a monoclonal antibody targeting ErbB2, been recently approved as the first molecularly targetd drug against gastric cancer." (PMID 22292935, 2012). "EGFR and ERBB2 expression in gastric cancer has been reported in many past studies." (PMID 21689422, 2011). "Reported rates of ERBB2 gene expression in gastric cancer range were from 9% to 38%." (PMID 21689422, 2011). "Moreover, the correlation between EGFR/ERBB2 expression in gastric cancer and prognosis remains controversial." (PMID 21689422, 2011). "ERBB2 gene amplification was observed in20.3% (14/69) of gastric cancer patients, including 24.4% (10/41) of the 41 patients with lymph node metastases and only 7.1% (2/28) of patients without lymph node metastases, representing a significant difference (P < 0.05)." (PMID 21689422, 2011). "It has been estimated that 2-27% of gastric cancers harbour ERBB2 amplifications and may be treated with ERBB2 inhibitors." (PMID 21781349, 2011). "EGFR and ERBB2 expression in gastric epithelial cells are indicators of malignancy and may prove useful as markers for poor prognosis in gastric cancer." (PMID 21689422, 2011). "The results showed that MIC-1 might participate in the malignant progression of human breast and gastric cancer cells that over-express ErbB2 through the transactivation of ErbB2 tyrosine kinase." (PMID 23554633, 2010). "Using clinicopathological and follow-up data from these 256 patients, we investigated whether ERBB2 amplification is a prognosis factor in different subgroups of gastric cancer patients." (PMID 19156142, 2009). "Interestingly, ERBB2 mutations were detected in four gastric adenocarcinomas, raising the possibility of testing a HER-2 inhibitor such as trastuzumab in gastric cancer patients selected based on this genetic criterion." (PMID 19924296, 2009). "Most gastric carcinomas showing ERBB2 amplification were of the intestinal/glandular type (81.6% of all positive cases, P=0.007), but this genetic alteration was also observed in diffuse/isolated cells, and solid and mixed carcinomas (7.9, 5.3, and 5.3% of positive cases, respectively)." (PMID 19156142, 2009). "Interestingly, in both Western and Eastern patients there is a correlation between gastric carcinomas with ERBB2 amplification and intestinal type: 81.6% in this study vs 86 and 84.2% reported in Eastern patients." (PMID 19156142, 2009). "The ERBB2 protein status was determined by IHC for the 463 gastric carcinoma tissues." (PMID 19156142, 2009). "In addition, overexpression of MUC4 in AGS, gastric cancer cells, increases both total and phosphorylated form of ErbB2." (PMID 18781152, 2008).
gastric cancer (continued). "By targeting ERBB2, ursolic acid may inhibit key signaling pathways involved in tumor growth and metastasis, presenting a promising alternative or complementary strategy for gastric cancer treatment." (PMID 40141751, 2025). "In gastric cancer, the fact that miR-497-5p inhibits GC cell motility, invasion, and proliferation by targeting ERBB2 suggests a potential theoretical basis and therapeutic target." (PMID 38911367, 2024). "Targeting ERBB2 implies that miR-497-5p may affect the biological function of gastric cancer cells." (PMID 38911367, 2024). "Moreover, mRNA level could define HER2 dependency and response to treatment in certain tumors, reported for a cholangiocarcinoma patient and a gastric cancer patient with high ERBB2 mRNA." (PMID 39931207, 2024). "Over-expression of ERBB2 in gastric cancer cells significantly reduced miR-497-5p's inhibitory effect on the malignant behavior of GC cells." (PMID 38911367, 2024). "Moreover, since the first study reporting the clinical benefit of afatinib in ERBB2-mutant lung adenocarcinoma in 2011, accumulating evidence has consistently demonstrated its clinical activity against various ERBB2-altered human malignancies, including lung, breast, and gastric cancers." (PMID 38067272, 2023). "In addition, TCGA whole exome sequencing dataset analyses showed that ERBB2‐nonamplified gastric cancer cases harbored higher mutation numbers, CD8A expression levels, and CYT scores." (PMID 37325934, 2023). "Furthermore, gastrointestinal cancers, such as colorectal cancer, gastric cancer, pancreatic cancer, and bile duct cancer, were related to low recommendation rates (<20%), wherein ERBB2 amplification, KRAS G12C, and microsatellite instability (MSI)‐High (MSI‐H) resulted in recommendations commonly." (PMID 36251535, 2023). "Besides, ERBB2 is widely altered in solid tumors, especially breast and gastric cancers." (PMID 35071000, 2021). "Therefore, we considered that HER2/c-erbB-2 might be related to the occurrence, development, invasion, and metastasis of gastric cancer." (PMID 33817143, 2019). "Human epidermal growth factor receptor 2 (Erbb2/HER2) overexpression, which was previously detected in invasive breast cancer, has now been implicated in advanced gastric cancer (GC) and gastroesophageal junction cancer (GEC)." (PMID 28124769, 2018). "Yet, the results obtained in our shRNA-mediated HER2 knockdown experiments suggest that this cell line is somewhat dependent on this signaling pathway, and ErbB2/HER2 signaling pathway can still be targeted to control the proliferation of this gastric cancer cell line." (PMID 29686309, 2018). "Trastuzumab was the first drug successfully used to treat ERBB2-amplified, advanced stage GC as demonstrated in the Trastuzumab for Gastric Cancer (ToGA) trial." (PMID 26267324, 2015). "However, a lack of reliable and accurate methods to assess the relationship between EGFR and ERBB2 gene status and protein expression in gastric cancer has limited correlative assessments with clinical parameters, including survival and sensitivity to targeted agents." (PMID 21689422, 2011). "The clinical significance of ERBB2 amplification/overexpression in gastric cancer remains unclear." (PMID 19156142, 2009). "We conclude that ERBB2 status may have clinical significance in subsets of gastric cancer patients, and that further studies are warranted to evaluate whether patients whose gastric carcinomas present ERBB2 amplification/overexpression may benefit from therapy targeting this surface receptor." (PMID 19156142, 2009). "In this context, evaluation of ERBB2 (HER2) alterations is clinically relevant, not only for well-known HER2-driven malignancies like breast or gastric cancer but also for all solid malignancies, as we showed in our cohort analysis." (PMID 40828885, 2025).
gastric cancer (continued). "ERBB2 (HER2) represents one of the most clinically relevant biomarkers in gastric cancer, with approximately 15–20% of gastric and gastroesophageal junction (GEJ) adenocarcinomas demonstrating ERBB2 overexpression or amplification." (PMID 40699829, 2025). "Hence, ERBB2 may be a miR-497-5p target gene, significantly expressed in gastric cancer." (PMID 38911367, 2024). "Human epidermal growth factor receptor-2 (HER2), also referred to as HER2/neu or ERBB2, is present in about 20% of gastric cancer cases." (PMID 38611014, 2024). "Both ERBB2 and CDK12 are located at chromosome 17q12, which is a highly amplified region in gastric cancer." (PMID 37325934, 2023). "The presence of neuromodulin, a ligand for ErbB3, leads to heterodimerization of ErbB2, ErbB3, and ErbB4, thereby reducing the cytotoxicity of T-DMI in gastric cancer cell lines." (PMID 37305567, 2023). "HER2 testing guidelines exist only for tumor types with approved HER2‐targeted therapies (i.e., breast and gastric cancers), but other solid tumors also exhibit perturbations in HER2 protein and ERBB2 gene levels." (PMID 37119523, 2023). "Receptor tyrosine kinase erythroblastic oncogene B2 (ERBB2), also known as human epidermal growth factor receptor 2 (HER2), represents an oncogenic driver and has been effectively targeted in breast and gastric cancer." (PMID 38138928, 2023). "In contrast to guidelines developed for breast and gastric cancers that also consider ERBB2 copy number, HER2‐positivity in KAMELEON was based solely on protein expression." (PMID 37119523, 2023). "Esophageal adenocarcinoma, gastric cancer, and colorectal cancer presented significantly higher MSI and TMB in the ERBB2-mutant group than in the ERBB2-wild-type group." (PMID 37754252, 2023). "EGFR signaling has been extensively studied in the context of gastric cancers with several EGF receptors, such as HER2 (Erbb2) and EGFR, which are found to be frequently overexpressed due to copy number amplification." (PMID 37386010, 2023). "In our cohort, the amplification event of ERBB2 determined by TSO500 was found in twenty-four (66.7%) specimens, much higher than the reported 6% prevalence of HER2-positive gastric cancer in Taiwan." (PMID 36612265, 2022). "Gastric cancers (GCs) that express human erb-b2 receptor tyrosine kinase 2 (ERBB2, also known as HER2) account for 7.3%–20.2% of GCs." (PMID 36059809, 2022). "The expression of ERBB2 and ERBB2d16 was examined using quantitative RT-PCR in the pretreatment gastrectomy specimens of 110 patients with HER2-overexpressing gastric cancer." (PMID 35463314, 2022). "ERBB2 and ATM levels both increases in liver cancer, stomach cancer and both decreases in kidney chromophobe cancer." (PMID 36056635, 2022). "Assessing Erb-b2 receptor tyrosine kinase 2 (ERBB2) amplification status in breast and gastric cancer is necessary for deciding the best therapeutic strategy." (PMID 33710417, 2021). "The top two ranking oncogene focal amplifications, ERBB2 and CCNE1, were the same in both gastric cancer and GCAs." (PMID 34764264, 2021). "MiR-133a inhibits the proliferation of gastric cancer cell SNU-1 and promotes SNU-1 cell apoptosis by modulating downstream ERBB2 (also called HER2, a member of EGFR family), and reducing the p-ERK1/2 and p-AKT expression." (PMID 33391416, 2021). "Recently, the presence of human epidermal growth factor receptor 2 (HER2; also known as ERBB2) expression in advanced gastric cancer (AGC) has played an important role in treatment." (PMID 32210254, 2020). "Intertumoral heterogeneity among actionable biomarkers including ERBB2, FGFR2 and EGFR has been observed to occur under therapeutic pressure in advanced gastric cancer." (PMID 32158697, 2020).
gastric cancer (continued). "HER2/c-erbB-2 and EGFR expression were related to the prognosis of gastric cancer patients and can be used as biomarkers of prognosis." (PMID 33817143, 2019). "Positive expression rates of HER2/c-erbB-2 and EGFR in gastric cancer tissue were significant higher than that of normal gastric tissue in patients with gastric cancer." (PMID 33817143, 2019). "Accordingly, overexpression of GPAA1 profoundly promoted the proliferation of gastric cancer cells, an effect that was counteracted by the administration of trastuzumab, a blocker simultaneously targeting EGFR and ERBB2." (PMID 31118109, 2019). "Genetic alterations in the EGFR, MET, ERBB2, and the PI3K/AKT pathway are often observed in gastric cancer." (PMID 31816819, 2019). "HER2/c-erbB-2 and EGFR protein expression was examined by immunohistochemical assay in gastric cancer tissue and corresponding paired normal gastric tissue of 67 patients of gastric carcinoma." (PMID 33817143, 2019). "We do also acknowledge that MKN45 cells, one of the gastric cancer cell lines used in this study, have amplified-MET and more likely to dependent on this pathway than ErbB2/HER2 signaling for their survival." (PMID 29686309, 2018). "Previous studies have demonstrated that miR-375 inhibits cell proliferation of gastric cancer cells by repressing JAK2, ERBB2, and YWHAZ18,46–48." (PMID 30258124, 2018). "Human epidermal growth factor receptor 2 (HER2/ErbB2) is a member of the EGFR family and is overexpressed in various types of cancer, including breast and gastric cancers." (PMID 29301363, 2018). "We also found that our novel RUNX inhibitor (Chb-M’) consistently led to the deactivation of the ErbB2/HER2 signaling pathway and was effective against several gastric cancer cell lines." (PMID 29686309, 2018). "However, in human breast or gastric cancer ErbB2 gene was found rather amplified and not mutated." (PMID 28286519, 2017). "In order to confirm the curbing role of miR-1296-5p in gastric cancer progress and metastasis, we transfected miR-1296-5p mimic into ERBB2-positive SNU-216 and NUGC-4 gastric cancer cells and then subjected them to cell migration and invasion assays." (PMID 28099468, 2017). "When trastuzumab, small molecular targeted drug CP724714, or interfering RNA against ERBB2 are applied, the EMT-like phenotype of gastric cancer cells is dramatically reversed." (PMID 28160563, 2017). "ERBB2-positivie gastric cancer cells, SNU-216 and NUGC-4 cells, were treated with herceptin (recombinant humanized anti-ERBB2 antibody) and then subjected to small G-protein activation assay." (PMID 28099468, 2017). "In ERBB2-positive gastric cancers, the miR-1296-5p expression is more suppressed in a majority of metastatic lymph node tissues compared to non-metastatic gastric cancer samples, suggesting that miR-1296-5p might play a role of tumor metastasis suppressor in ERBB2-positive gastric cancer." (PMID 28099468, 2017). "Human epidermal growth factor receptor 2 (HER2, also known as ERBB2) is frequently amplified or overexpressed in up to 30% of advanced-stage gastric cancers." (PMID 27581465, 2016). "Overexpression of ErbB1 (EGFR) and ErbB2 (HER-2) is found in 27–64% and 6–34% of gastric cancer, respectively." (PMID 25945346, 2015). "In regards to esophageal and gastric cancer, higher EGFR and ERBB2 levels have been correlated with poor esophageal and gastric cancer survival." (PMID 23874846, 2013). "ErbB2 gene amplification in a cluster pattern (red) was observed in MGC-803, BGC-823 and SGC-7901 cells, erbB2 overexpression only in human SGC-7901 gastric cancer cell." (PMID 23658725, 2013). "Oncogenes in gastric cancer, such as MYC (mapped to chromosome 8q24), KRAS (12p12), and ERBB2 (17q12), are located in such amplified regions." (PMID 22591714, 2012). "Human Epidermal Growth Factor Receptor-2 HER2 (erbB2, HER2/neu) is highly expressed in some breast cancers, ovarian and gastric cancers." (PMID 22754305, 2012).
gastric cancer (continued). "Fluorescence in situ hybridization (FISH) and immunohistochemistry were used to analyze ERBB2 and EGFR gene amplification and protein expression in 69 cases of gastric cancer." (PMID 21689422, 2011). "We combined this data with results from histopathological and immunohistochemical analyses to determine the relationship between ERBB2 and EGFR expression status and clinicopathological variables in gastric cancer." (PMID 21689422, 2011). "The goal of this study was to investigate ERBB2(HER2) and EGFR gene amplification and protein expression in gastric cancer." (PMID 21689422, 2011). "ERBB2 and PERLD1 have been previously been reported to be gained and overexpressed in gastric cancers." (PMID 20187983, 2010). "Furthermore, in our consecutive series of gastric cancer patients, we found ERBB2 amplification in two early gastric carcinomas (stage IA) in similar studies, further supporting the idea that ERBB2 amplification may occur at an early stage in gastric carcinogenesis." (PMID 19156142, 2009). "ERBB2 overexpression (2+ and 3+) and amplification (ratio ERBB2/CEP17⩾2) were found in 43 (9.3%) and 38 (8.2%) gastric carcinomas, respectively." (PMID 19156142, 2009). "Other studies have shown that in SRCC type gastric cancer cells, MUC4 is required for the activation of ErbB2." (PMID 18781152, 2008). "In our previous research in gastric cancer xenografts and cell lines, amplified and overexpressed genes detected in this region were the well-known TOPO2A and ERBB2, and one uncharacterised EST." (PMID 12799636, 2003). "Two of the most investigated genes are ERBB2 and TOPO2A making them possible prognostic markers of gastric cancer." (PMID 12799636, 2003). "Unlike in breast and gastric cancers, where HER2 amplification and overexpression guide therapy, ERBB2-mutant NSCLC poses unique therapeutic challenges due to the structural nature and lower immunogenicity of the mutations." (PMID 41426315, 2025). "The standard first-line treatment for ERBB2-negative advanced gastric cancer typically involves platinum-based combinations, with oxaliplatin plus fluoropyrimidines being widely used in Japanese clinical practice." (PMID 40699829, 2025). "Amplifications of ERBB2 and CCND3 were significantly more frequent in ELF3/HNF4A up-regulated gastric cancers (28.6% and 20.4%, respectively) compared with the group of non-up-regulated cancers (2.4% and none, Student’s t-test p = 0.0006 and 0.001, respectively)." (PMID 41425714, 2025). "In this study, the potential target of HL-RG in the treatment of gastric cancer was studied Through PPI network analysis and molecular pairing, TGFB1, CCND1, MMP9, ERBB2, CAT, and PPARα may be the core targets of HL-RG in the treatment of RCC." (PMID 41305721, 2025). "Furthermore, a comprehensive multi-omic analysis of malignant gastric cancers revealed genomic amplifications of established cancer driver genes such as EGFR, ERBB2, MET, FGFR2, and CD44 in gastric cancer with peritoneal metastasis." (PMID 41009730, 2025). "While ERBB2/HER2 aberrations are well-characterized in breast and gastric cancers, our findings highlight the prevalence and potential clinical relevance of ERBB2/HER2 alterations in underrepresented cancer types, such as salivary glands, uterine, and cholangiocarcinomas." (PMID 40828885, 2025). "The locus at 17q12 erb‐b2 receptor tyrosine kinase 2 (ERBB2) has been heavily amplificated and overexpressed in gastric cancer (GC), but it remains to be elucidated about the clinical significance of the co‐amplification and co‐overexpression of PGAP3 gene located around ERBB2 in GC." (PMID 37386793, 2023). "An analysis of gastric cancer lymph node metastasis revealed the presence of ERBB2, CLDN11 and CDK12, as markers of lymph node metastasis, which may contribute to lymph node metastasis in gastric cancer." (PMID 37305583, 2023).